HAND1 (heart and neural crest derivatives expressed 1)
Description:
Transcription factor that plays an essential role in both trophoblast giant cell differentiation and in cardiac morphogenesis (By similarity). Binds the DNA sequence 5'-NRTCTG-3' (non-canonical E-box) (By similarity). Acts as a transcriptional repressor of SOX15 (By similarity). In the adult, could be required for ongoing expression of cardiac-specific genes.
Synonyms: bHLHa27; eHAND; Thing1; Hxt
Tractability: No criterion of Open Targets' tractability assessment is met for any kind of drug.
Gene: Protein-coding gene on chromosome 5 (154,474,969 to 154,478,356, reverse strand). Ensembl gene ENSG00000113196.
Subcellular location: Nucleus, nucleoplasm; Nucleus, nucleolus
Subcellular location (Human Protein Atlas): Nucleoplasm; Nuclear bodies; Nuclear membrane
Pathways (Reactome):
Developmental Biology: Cardiogenesis
Gene Ontology:
Molecular function: bHLH transcription factor binding; DNA-binding transcription factor activity, RNA polymerase II-specific; DNA-binding transcription repressor activity, RNA polymerase II-specific; protein binding; RNA polymerase II cis-regulatory region sequence-specific DNA binding; RNA polymerase II-specific DNA-binding transcription factor binding; transcription cis-regulatory region binding; DNA-binding transcription activator activity, RNA polymerase II-specific; identical protein binding; RNA polymerase II transcription regulatory region sequence-specific DNA binding; transcription coregulator binding; DNA binding; DNA-binding transcription factor activity; enzyme binding; protein dimerization activity; protein homodimerization activity; sequence-specific DNA binding
Biological process: blastocyst development; cardiac left ventricle formation; cardiac right ventricle formation; cardiac septum morphogenesis; negative regulation of transcription by RNA polymerase II; positive regulation of transcription by RNA polymerase II; trophectodermal cell differentiation; ventricular cardiac muscle tissue morphogenesis; angiogenesis; embryonic heart tube development; heart development; heart looping; regulation of transcription by RNA polymerase II; trophoblast giant cell differentiation
Cellular component: cytoplasm; nucleus; RNA polymerase II transcription regulator complex; chromatin; nucleolus; nucleoplasm
Genetic constraint (gnomAD): Loss-of-function variants: 8 observed, 12.15 expected, observed/expected ratio (o/e) 0.66, 90% interval 0.38 to 1.19. The upper end of that interval is the gene's LOEUF score, 1.19, which puts it in group 5 of 6, group 1 being the genes least tolerant of losing a copy. Missense variants: 295 observed, 299.11 expected, observed/expected ratio (o/e) 0.99, 90% interval 0.9 to 1.09. Synonymous variants: 127 observed, 128.57 expected, observed/expected ratio (o/e) 0.99, 90% interval 0.85 to 1.14.
Gene-disease validity (ClinGen):
ClinGen rates the evidence that HAND1 causes each of these diseases.
congenital heart disease (autosomal dominant): Moderate. A heart disease that is present at birth.
Homologues: Orthologues: chimpanzee HAND1 (99% identical), macaque HAND1 (99% identical), dog HAND1 (97% identical), pig HAND1 (97% identical), guinea pig HAND1 (97% identical), rabbit HAND1 (97% identical), rat Hand1 (94% identical), mouse Hand1 (93% identical), tropical clawed frog hand1 (64% identical), Drosophila melanogaster Hand (33% identical), Drosophila melanogaster twi (20% identical), Caenorhabditis elegans hlh-8 (18% identical), and 2 more. Paralogues in human: HAND2 (55% identical), TWIST1 (23% identical), PTF1A (22% identical), SCX (22% identical), TCF15 (22% identical), TWIST2 (22% identical), MSC (20% identical), TCF21 (19% identical), TCF24 (18% identical), TCF23 (18% identical), BHLHA9 (15% identical), FIGLA (15% identical), and 1 more.
Diseases named in the same sentence as HAND1 in open-access papers:
HAND1 is named in the same sentence as 49 diseases in open-access papers, as found by Europe PMC text mining. Sharing a sentence is not in itself a finding about the gene and the disease. The quoted sentences say what the papers report.
congenital heart disease (9 papers, 2012 to 2026). "The association with the genes NKX2-5, NOTCH1, GATA4, GATA6 and HAND1 links trabeculation to congenital heart disease (CHD)." (PMID 39567769, 2024). "The HAND1 gene, which encodes heart and neural crest derivatives expressed 1, is linked to congenital heart disease (CHD) and is expressed in placental trophoblasts and endothelial cells in various mouse models." (PMID 38778305, 2024). "Although mutations of NKX2-5, HAND1 and TBX20 have been found in patients with TOF, they are present only in a small percentage of patients with congenital heart disease." (PMID 22672592, 2012).
heart failure (5 papers, 2011 to 2025). Inability of the heart to pump blood at an adequate rate to meet tissue metabolic requirements. "Heart and Neural Crest Derivatives Expressed 1 (HAND1) is a key TF involved in the placentation and morphogenesis of the heart, and its deficiency during embryogenesis can cause congenital cardiac defects or adult heart failure." (PMID 38414063, 2024). "By targeting Hand1, the downstream effector, this work suggests a promising molecular target for gene therapy of heart failure, potentially guiding the development of novel molecular interventions to enhance cardiac repair." (PMID 39899693, 2025). "We have previously found that adult Hand1 up-regulating hearts display a heart-failure-like phenotype of low threshold for ventricular arrhythmia and a diastolic defect." (PMID 24086110, 2013). "Here, we generated transgenic mice with over-expression of Hand1 and Twist1 mutants (to mimic or to abolish phosphorylation) in cardiomyocytes and found pathological cardiac remodeling leading to heart failure and sudden death." (PMID 21559426, 2011). "Altogether, we propose that the potential of endogenous regenerative properties in adult hearts by the Foxp1‐Usp20‐HIF1ɑ‐Hand1 signaling pathway might represent a future promising therapeutic approach for heart failure." (PMID 39899693, 2025). "This suggests that Hand1 could serve as a novel molecular target for gene therapy in the treatment of heart failure." (PMID 39899693, 2025). "This pathway may be of significance in the adult during heart failure, as Hand1 is one of the “fetal” genes up-regulated in the failing cardiomyocyte." (PMID 24086110, 2013). "Importantly, our findings suggest that Hand1, a downstream target in this pathway, could serve as a promising molecular target for gene therapy in the treatment of heart failure." (PMID 39899693, 2025). "Interestingly, the genes involved in oxidative phosphorylation and TCA (citrate) cycle were found with reduced levels in Hand1-DD heart suggesting that decreased metabolism may result in heart failure." (PMID 21559426, 2011). "But that's not to say that Hand1 finds no use in adult life; in fact, the authors note that Hand1—and therefore glycolytic metabolism—is re-expressed in the hearts of adults undergoing heart failure." (PMID 24086108, 2013).
atrial septal defect (4 papers, 2011 to 2026). Interauricular communication is a congenital malformation characterized by a communication between the atrial chambers of the heart. "We also analyzed the 49 heart tissues of 28 patients for HAND1 mutations and detected a nonsynonymous mutation (c.252G>T, p.R84L) in the right atrium of an atrial septal defect (ASD) patient (99 NM)." (PMID 24376681, 2013).
Tetralogy of Fallot (4 papers, 2013 to 2023). A congenital cardiac malformation comprising pulmonary stenosis, overriding aorta, ventricular septum defect, and right ventricular hypertrophy. "NKX2-5, GATA4 and HAND1 are essential for heart development, however, little is known regarding their epigenetic regulation in the pathogenesis of tetralogy of fallot (TOF)." (PMID 24182332, 2013). "In twins with tetralogy of Fallot (TOF), it has been observed that a good number of genes in cardiac tissue have been linked to differential DNA methylation like the NKX2-5 (NK2 Homeobox 5) and HAND1 (Heart And Neural Crest Derivatives Expressed 1) genes." (PMID 34540478, 2021).
colorectal cancer (3 papers, 2019 to 2024). A primary or metastatic malignant neoplasm that affects the colon or rectum. "Intriguingly, ectopic expression of HAND1 triggers terminal differentiation and impedes the growth, proliferation, and xenograft tumour formation of colorectal cancer cells." (PMID 38689296, 2024). "Consistent with our results, HAND1 has been reported to be silenced by methylation in other cancers including colorectal cancer 12-15, 17-19." (PMID 36594085, 2023). "The heart and neural crest derivatives expressed 1 (HAND1), belonging to the basic helix-loop-helix family of transcription factors, is showed to be a tumor suppressor gene in colorectal cancer." (PMID 31565069, 2019).
medulloblastoma (3 papers, 2022 to 2023). A malignant, invasive embryonal neoplasm arising from the cerebellum. "However, in medulloblastoma, HAND1 expression may be the key to weaken EMT, which may be different from previous research conclusions, but it may be related to different apparent modifications of HAND1 in tumors." (PMID 35281077, 2022).
seminoma (3 papers, 2016 to 2021). A radiosensitive malignant germ cell tumor found in the testis (especially undescended), and extragonadal sites (anterior mediastinum and pineal gland). "An interesting candidate gene is FOXA2, which is up‐regulated during the differentiation of TCam‐2 into a mixed non‐seminoma and was predicted to interact with many differentiation markers, such as AFP, HAND1 and EOMES42." (PMID 28244655, 2017).
cardiac arrhythmia (2 papers, 2011 to 2013). Any disturbances of the normal rhythmic beating of the heart or MYOCARDIAL CONTRACTION. "TG mice with over-expression of Hand1-WT in heart did not display apparent phenotype by 32 weeks, which was in consistence with a recent report showing that Hand1-WT TG mice displayed mild hypertrophy but were predisposed to cardiac arrhythmia." (PMID 21559426, 2011).
cardiac hypertrophy (2 papers, 2011 to 2023). "HAND1/2 is expressed in the adult heart and is downregulated in cardiomyopathies, it modulates cardiac hypertrophy and is also involved in heart, vascular, gastrointestinal tract, limb and neuronal development." (PMID 38110859, 2023). "Two lines with a relatively low Hand1-DD expression (designated DD2low and DD63low) developed heart hypertrophy at 2 months and the majority of these mice died at 4–5 months." (PMID 21559426, 2011). "Two mice lines expressing high-level Hand1-DD (designated DD80high and DD68high) displayed heart hypertrophy at 1 month that became more severe at 2 months." (PMID 21559426, 2011). "In human patients with cardiomyopathy as well as rodent models of cardiac hypertrophy, Hand1 gene expression levels were found reduced suggesting a correlation between Hand1 levels and heart remodeling." (PMID 21559426, 2011). "HAND1/2 is expressed in the heart tissues, modulating cardiac hypertrophy." (PMID 38110859, 2023).
cardiomyopathy (2 papers, 2011 to 2024). A disease of the heart muscle or myocardium proper. "Researchers are interested in HAND1/2’s possible role as a tumour suppressor and how its downregulation may contribute to cardiomyopathy development." (PMID 38689296, 2024). "Hand1 and Hand2 were found involved in the development of cardiomyopathy in rodents and human." (PMID 21559426, 2011).
endometrial cancer (2 papers, 2013 to 2017). Primary or metastatic malignant neoplasm involving the endometrium (mucous membrane that lines the endometrial cavity). "The Hand1 protein has been isolated in endometrial cancer samples and has been expressed preferentially in mESCs cultured with BMP4, allowing for trophoblast differentiation from mESCs, a common pathway with humans." (PMID 28716123, 2017). "All EpiMods demonstrated strong enrichment for biological terms, with the HAND2 EpiMod itself highly enriched for other transcription factors (e.g., GATA4, HEY2, HOXD13, PHOX2A, HAND1), all of which were also hypermethylated in endometrial cancer." (PMID 24265601, 2013).
gastric cancer (2 papers, 2023 to 2024). A primary or metastatic malignant neoplasm involving the stomach. "HAND1 protein expression was evaluated by immunohistochemistry in 10 normal gastric mucosa biopsy specimens and 165 gastric cancer cases." (PMID 36594085, 2023). "Furthermore, studies demonstrated that the HAND1 gene was hypermethylated and downregulated in gastric cancer and is believed to function as a tumour suppressor gene." (PMID 38689296, 2024).
gastrointestinal stromal tumor (2 papers, 2020 to 2022). "HAND1 is expressed in invasive gastrointestinal stromal tumors (GIST)." (PMID 35281077, 2022). "One report indicated that astrocytic HAND1 was found to be unique in metastatic gastrointestinal stromal tumor (GIST) and might work as a transcriptional amplifier of the oncogenic GIST program." (PMID 33228590, 2020).
myocardial infarction (2 papers, 2013 to 2022). Gross necrosis of the myocardium, as a result of interruption of the blood supply to the area, as in coronary thrombosis. "In vivo models of myocardial infarction will be necessary to investigate formally a role for modulating Hand1 levels in myocardial ischaemia protection." (PMID 24086110, 2013). "Studies are now ongoing to investigate formally a potential role for Hand1 in myocardial infarction." (PMID 24086110, 2013). "Furthermore, we show that increasing Hand1 expression in adult transgenic hearts is protective against myocardial infarction, suggesting that a hypoxia–Hand1 pathway may also be of importance in the adult heart." (PMID 24086110, 2013).
neuroblastoma (2 papers, 2023 to 2025). Neuroblastoma (NB) is the most common solid, extracranial childhood tumor. "These NIPBL-bound MYCN peaks are highly enriched for motifs of core regulatory circuitry (CRC) transcription factors such as GATA3, PHOX2A, HAND1, and HAND2, which contribute to the maintenance of the neuroblastoma oncogenic cell identity." (PMID 40867243, 2025). "In contrast, NIPBL peaks that overlapped with MYCN binding were significantly enriched for motifs recognized by core regulatory circuitry (CRC) transcription factors critical to neuroblastoma cell identity, including GATA3, PHOX2A HAND1, and HAND2." (PMID 40867243, 2025).
asthma (1 paper, 2014). "On account of regulatory impact factor (RIF) score, HAND1, PTK7, and ZIC3 were the potential asthma-related factors." (PMID 24790987, 2014). "In addition, HAND1, PTK7, and ZIC3 were found to be potential asthma-related factors considering their TIF values." (PMID 24790987, 2014). "However, further experimental verification is needed on the possible roles of HAND1, PTK7, and ZIC3 in asthma proposed in this study." (PMID 24790987, 2014). "We suggested that HAND1, PTK7, and ZIC3 may be used as biomarkers for asthma; however, more work is needed to validate our result." (PMID 24790987, 2014). "A recent study provides evidence that HAND1 is indeed an important regulator of the interventricular boundary, but the role of HAND 1 in asthma has not been reported." (PMID 24790987, 2014).
atrioventricular septal defects (1 paper, 2014). "HAND1 may be involved in the occurrence of atrioventricular septal defects." (PMID 25165856, 2014).
colon cancer (1 paper, 2013). "Among the group of the most consistently hypermethylated genes in both human colon cancer and mouse intestinal adenoma (48 genes), we found Cdh4, Crabp1, Crmp1, Dbc1, Duox1, Grm7, Hand1, Hs3st2, Pcdh17 and Pdpn, which have previously been suggested as cancer biomarkers." (PMID 23408899, 2013).
colorectal tumors (1 paper, 2019). "As a developmental regulator, HAND1 is silenced in over 90% of human primary colorectal tumors." (PMID 31639059, 2019).
coronary artery disease (1 paper, 2022). "For instance, allele rs55730499-T associated with increased level of LDL-C and the risk of coronary artery disease was predicted to create binding sites for transcription factors acting as activators (NR1H, AHR::ARNT, IRF) or repressors (HAND1) of gene expression." (PMID 35203469, 2022).
Gastric Metaplasia (1 paper, 2019). Intestinal metaplasia of the gastric mucosa is an intermediate precancerous gastric lesion in the gastric cancer cascade from chronic gastritis and atrophy to dysplasia and adenocarcinoma. "For example, hypermethylation of APC, THBD, and HAND1 was associated with gastric metaplasia." (PMID 31537016, 2019).
hydrops (1 paper, 2010). "However, close inspection of individual profiles revealed that within the SCNT-hydrops group, there were individuals who showed aberrant hypo- or hypermethylation, particularly in the IGF2 exon 10 DMR, KCNQ1OT1, SNRPN and HAND1 regions." (PMID 20205951, 2010).
Hypertension (1 paper, 2020). The presence of chronic increased pressure in the systemic arterial system. "Finally, the TF (HAND1, E4BP4, ESR1, VBP, ELK-1, POU3F2) associated with LV remodeling in hypertension were confirmed to act a crucial role in correlated heart diseases." (PMID 32664164, 2020).
hypoplastic left heart syndrome (1 paper, 2020). Hypoplastic left heart syndrome (HLHS) refers to the abnormal development of the left-sided cardiac structures, resulting in obstruction to blood flow from the left ventricular outflow tract. "Notably, their study suggested that many hearts with different forms of hypoplastic left heart syndrome had the same A126fs variant in HAND1, and their findings have not been confirmed by subsequent genomic studies or animal modelling of the variant y." (PMID 32426881, 2020).
lung carcinoma (1 paper, 2022). "Several genes, such as HOXC12, HAND1, VIPR2, KRT20, MMP24, and VIPR2, were discovered, and their special roles at different omics levels of lung cancer were confirmed." (PMID 35155435, 2022). "Apart from HAND1, BMP3 together with BMP5 has been considered potential multi-omics level lung cancer biomarkers according to recent publications." (PMID 35155435, 2022).
lymph node metastasis (1 paper, 2023). "In univariate analysis, HAND1 expression (p<0.001), age (p=0.012), histopathological grading (p=0.047), depth of invasion (p<0.001), lymph node metastasis (p<0.001), distant metastasis (p<0.001), and TNM stage (p<0.001) were significantly associated with OS in GC patients." (PMID 36594085, 2023).
omphalocele (1 paper, 2025). Omphalocele is an embryopathy classified in the group of abdominal celosomias and is characterized by a large hernia of the abdominal wall, centered on the umbilical cord, in which the protruding viscera are protected by a sac. "To understand where the Hand1 expression domain could be contributing to omphalocele in the Hand1Hand2/Hand2 embryos beyond expression within the dorsal mesentery and gut, we interrogated Hand1 expression using our Hand1lacZ/+ allele at E11.5." (PMID 40960281, 2025). "The discovery of omphalocele in the majority of Hand1Hand2/Hand2 neonates, combined with structural and conduction heart defects, suggests a unique role for HAND1 during gut and cardiac morphogenesis." (PMID 40960281, 2025). "Interestingly, Hand1 conditional deletion employing Tlx2-cre also reveals an omphalocele phenotype." (PMID 40960281, 2025). "Clearly, the role of HAND1 within the lateral mesoderm derivatives is important and the roles of HAND1 within asymmetric gene regulatory networks that modulate tissue looping outside of the heart may provide insights into congenital conditions such as omphalocele." (PMID 40960281, 2025). "RNA-seq analysis reveals that most of the altered gene expression observed in Hand1 mutants is restored; however, the majority of Hand1Hand2/Hand2 progeny die as neonates with omphalocele, suggesting that HAND2 cannot fully rescue HAND1 function within ventral body wall, dm and umbilical tissues." (PMID 40960281, 2025).